CD4 (CD4 molecule)
Diseases named in the same sentence as CD4 in open-access papers (continued):
Sharing a sentence is not in itself a finding about the gene and the disease.
nasopharyngeal carcinoma (continued). "Furthermore, reduced T-cell-mediated anti-tumor immune responses have been correlated with reduced circulating CD4+ T cells in nasopharyngeal carcinoma (NPC) patients." (PMID 36005179, 2022). "Therapeutic EBV vaccines have been designed and tested in nasopharyngeal carcinoma (NPC) mainly aimed at EBNA1, LMP2, and have shown immunogenicity by inducing activated CD4+ and CD8+ T cells responses." (PMID 33329567, 2020). "Their data showed that application of mixed probiotics led to an improved immunity (increased CD3, CD4, and CD8 T-cells) in patients with nasopharyngeal carcinoma receiving radiotherapy and improved intestinal homeostasis in head and neck irradiated patients and rats." (PMID 39359935, 2024). "Actually, CD4/CD8 ratio was a sensitive and stable marker of anti-tumor cellular immunity and a higher CD4/CD8 ratio was related to better distant metastasis-free survival in patients with nasopharyngeal carcinoma treated by intensity modulated radiotherapy." (PMID 36138265, 2023). "Therefore, this study was aimed to elucidate the association with EBV oncoproteins (EBNA1 and LMP1), immune markers (CD4, CD8, and FOXP3) from nasopharyngeal cancer microenvironment with tumor progression." (PMID 35963999, 2022). "In nasopharyngeal carcinoma (NPC), miR-24-3p is profoundly upregulated in TDEs that can be delivered into T cells, where it then inhibits the percentage of CD4+ T cells and decreases the production of IFN-γ and IL-17 while provoking the augment of CD4+ Foxp3+ T cells (Tregs)." (PMID 35663957, 2022). "Interestingly, exosomes of nasopharyngeal carcinoma origin promote the proliferation of CD4+ CD25− T cells and their conversion to CD4+ CD25+ regulatory T cells." (PMID 35126514, 2022). "We then isolated CD4 positive and CD4 negative cells in surgically obtained samples of recurrent nasopharyngeal carcinoma." (PMID 34422839, 2021). "Vesicular microRNAs in the serum of patients with nasopharyngeal carcinoma influenced T-cell differentiation and activation through suppression of the MAPK1 signaling pathway, while EVs with a high amount of miR-24–3 reduced CD4+ and CD8+ T-cell proliferation by targeting FGF11." (PMID 36612080, 2022). "In nasopharyngeal carcinoma (NPC), the same family of HMGB2, high mobility group box 1 (HMGB1), the direct target of dead box helicase 5 (DDX5), is upregulated by the NAT10-mediated ac4C modification of DDX5, which inhibits the T-cell immunity of CD4 + and CD8 + T cells and promotes NPC progression." (PMID 41316475, 2025).
nephritis (36 papers, 2009 to 2025). Inflammation of renal tissue. "In this study, CD4+ CXCR5+ and CD4+ CXCR5+ ICOS+ Tfh cells were abnormally elevated in children with non-nephritis-type HSP, and were significantly associated with PGA-IgA, especially CD4+ CXCR5+ ICOS+-activated Tfh cells." (PMID 34250253, 2021). "Comparative analysis of CD4+CD25-Foxp3+ T cells in SLE patients revealed a significant association of this newly described cell population with active nephritis." (PMID 24774748, 2014). "Furthermore, transfer of CD4+ T cells from scurfy mice, but not from WT controls, induced autoantibody production as well as pneumonitis, nephritis and severe skin disease in CD4+ T cell-deficient B6/nude mice." (PMID 25890083, 2015). "However, the underlying mechanism of subsequent renal tissue damage caused by cytotoxic CD4 + CD28− T cells in SLE with nephritis remains unknown." (PMID 36320075, 2022). "For immunofluorescence assay, we observed that CD4+CXCR5+ T cells were significantly recruited at the site of nephritis of LN mice." (PMID 41164191, 2025). "So, when assessing the risk of renal impairment during SLE with CD4+CD8+ DPT cell proportion, we can effectively exclude the interference of NS and nephritis." (PMID 36625011, 2022). "In the group with inactive nephritis, significantly higher percentage and absolute count of CD4+CD25+Foxp3+ regulatory cells have been observed compared to the group with active LN." (PMID 27156107, 2016). "Longitudinal analysis of patients with active nephritis revealed a decline in CD4+CD25-Foxp3+ T cells under cyclophosphamide treatment in parallel to a drop in the extent of proteinuria and the disease activity." (PMID 24774748, 2014). "In addition, it is well established that CD4+ T-cell activation is an important mechanism in early anti-GBM nephritis and can mediate further immune response in ways like producing cytokines and recruiting downstream inflammatory cells." (PMID 40299471, 2025). "Furthermore CD4+CD25-Foxp3+ T cells were also detected in the urine sediment of patients with active nephritis." (PMID 24774748, 2014). "Next we analyzed CD4+CD25-Foxp3+ T cells in patients with nephritis in more detail." (PMID 24774748, 2014). "Interestingly, patients with renal involvement, especially patients with active nephritis, displayed increased proportions of CD4+CD25-Foxp3+ T cells, suggesting that the observed increase was mainly associated with renal organ involvement." (PMID 24774748, 2014). "Using multicolor fluorescence histochemical staining on renal biopsy tissues of patients with IgAN, we revealed that Tfh cells (CD4+ICOS+) were present in the kidney and mainly distributed around the glomeruli affected by nephritis." (PMID 35983053, 2022). "The proportion of CD4+CD8+ DPT cells in the LN group is significantly higher than those in both NS and nephritis groups." (PMID 36625011, 2022). "We demonstrated neutralizing IGFBP2-downregulated CD4+ T cell activation, upregulated the ratio of Treg, downregulated AKT/mTOR/4E-BP1 pathway, and significantly improved nephritis in MRL/lpr mice." (PMID 36008635, 2022). "To further determine the impact of CD4+CD8+ DPT cells on the development of LN, we compared the laboratory test results between the nephritis group and the LN group." (PMID 36625011, 2022). "Therefore, T-cell-driven kidney inflammation could be promoted by CD4+ instead of CD8+ T-cells." (PMID 31171837, 2019). "The number of white blood cells was positively correlated with IgA level (r = 0.260, P = 0.003) and negatively correlated with the proportion of CD4+ T cells (r = −0.298, P = 0.001) in children with HSP along with nephritis." (PMID 25514176, 2014). "CD154 surface protein levels were increased in CD4 T cells from SLE patients as compared with controls, and this increase correlated with the presence of nephritis and increased CD154 transcription rates." (PMID 22952582, 2012).
nephritis (continued). "Various immune cells, such as neutrophils, dendritic cells (DC), macrophages, natural killer (NK) cells, NKT cells, CD4 + T cells and regulatory T cells (Tregs), are activated after AKI incidence and participate in kidney inflammation, with neutrophils, DC and Tregs playing important roles." (PMID 39011500, 2024). "However, the levels of IL-6 (P < 0.05) and IFN- γ (P < 0.05) were still negatively correlated with CD4+/CD8+, and the concentration of IL-6 (P < 0.05) was still positively correlated with the occurrence of nephritis." (PMID 33882880, 2021). "Despite impaired DC migration, effector T cells including both CD4+ and CD8+ T cells rather increased in the peripheral tissue in the CCR7KO mice which exacerbated disease condition for airway allergy and nephrotoxic serum nephritis in the CCR7KO mice." (PMID 26908454, 2016). "As we also observed an increase of CD4+CD25-Foxp3+ T cells in cyclophosphamide-treated patients who suffered from active nephritis we compared CD4+CD25-Foxp3+ T cells in patients with active and no active organ involvement." (PMID 24774748, 2014). "In addition we also observed significant correlation between the CD4+CD25-Foxp3+ T cells and the extent of proteinuria, reflecting the disease activity in patients with active nephritis." (PMID 24774748, 2014). "Patients with nephritis had a significantly higher percentage of CD4+ T-lymphocytes expressing OX40 than those without nephritis." (PMID 21245596, 2011). "Expression of OX40 on CD4+ lymphocytes was significantly higher among SLE patients with nephritis than among those without nephritis." (PMID 21245596, 2011). "In addition, the proportion of CD4 + CD28− T cells in SLE patients with nephritis was significantly higher than that in those without nephritis (16.94 ± 2.562 vs. 4.687 ± 0.88, P = 0.012)." (PMID 36320075, 2022). "Moreover, the frequency of IL-1R8+ CD4+ T cells was further reduced in SLE patients with nephritis, compared with those without nephritis." (PMID 27148268, 2016). "Since the frequency of both activated Teffs and Tregs was enhanced in the spleens of Sn−/− mice, the net outcome on CD4 T cell function could be neutral and help explain why the severity of nephritis was similar regardless of the genotype." (PMID 24286366, 2013).
ovarian tumor (36 papers, 2011 to 2025). "Ovarian tumor-associated CD14+ myeloid cells are chemo-attractive for CD4+ T cells, and are strongly immunosuppressive for dendritic cell-stimulated tumor antigen-specific T cell responses." (PMID 26343197, 2015). "Strikingly, only 2.1% and 1.3% were dominated by Treg and other CD4+ T cells, respectively, suggesting that clonally expanded CD4+ T cells are more prominent in the lung TME than in ovarian tumors." (PMID 40777278, 2025). "The left ovarian tumor, which had increased in size, exhibited fewer tumor-infiltrating CD4-positive and CD8-positive cells compared to the uterine tumor, suggesting different therapeutic responses between the two lesions." (PMID 39758791, 2025). "Studies show ovarian tumor-derived CD4+CD25+ Tregs exhibit IL-2-dependent Th17 plasticity under CD3/APC stimulation, revealing microenvironmental modulation of Treg function." (PMID 40703514, 2025). "FAM111B-positive cells (p = 0.0178), CD8+ T cells (p = 0.0245), CD4+ T cells (p = 0.0319), Tregs (p = 0.0178), CD4+ Teff cells (p = 0.0367), and DCs (p = 0.0140) were primarily enriched in other types of ovarian tumors relative to mucinous carcinomas." (PMID 40564014, 2025). "RT-PCR was used to detect the expression levels of chemokine receptor-related differential genes on CD4+ T cells in peripheral blood and ovarian tumor tissues." (PMID 37950246, 2023). "In the boxplot of the tumor microenvironment (TME) cell composition, we are able to see that the CD4 memory resting T cells, Macrophages M2 and Macrophages M0 compost most of the microenvironment in ovarian tumor cells." (PMID 37597098, 2023). "Bioinformatics analysis was used to compare the transcriptome differences between CD4+ T cells in the peripheral circulation and infiltrated in ovarian tumor tissues." (PMID 37950246, 2023). "CD4+CCR8+ Tregs are the main type of infiltrating CD4+ Tregs in ovarian tumor tissues, which have stronger immunosuppressive phenotypes, secrete more inhibitory cytokines and have stronger proliferation ability." (PMID 37950246, 2023). "In previous studies, the elevated proportion of CD4+ CD25+ Treg cells in the total CD4+ T cell population was observed in several different human cancers, including lung, breast, and ovarian tumors." (PMID 35309296, 2022). "In contrast, in primary to metastatic ovarian tumor sites, OV_GSE118828 exhibited more cell types, including CD4 T conventional cells, myofibroblasts, fibroblasts and endothelial cells." (PMID 34966389, 2021). "Our data suggests that in addition to CD8+ T cells, MHCII and CD4+ T cells were also necessary to mediate the antitumor response induced by uracil auxotrophs to ID8DV ovarian tumors." (PMID 27447180, 2016). "In the present study, B-ALL cell line Nalm-6 also promoted the differentiation and expansion of Th17 cells from CD4+ T cells, similar to ovarian tumor cells." (PMID 27176825, 2016). "In tumor-containing ovaries, CD4+ T cells occurred in the stroma of both early stage and late stage ovarian tumors and were less frequent than either CD8+ or Bu1a+ cells." (PMID 24040191, 2013). "B cells and CD8+ T cells were seen in ovarian tumors of the hen with relatively high frequency, while CD4+ cells were detected at a relatively lower frequency." (PMID 24040191, 2013). "Similar to flow cytometry, Bu1a+ cells and CD8+ T cells were more numerous than CD4+ T cells in normal ovary and early and late stage ovarian tumors." (PMID 24040191, 2013).
ovarian tumor (continued). "Additionally, our study shows that daily restraint stress significantly changes the immune cell composition in the ovarian tumor microenvironment, marked by greater infiltration of F4/80+ macrophages and reduced presence of CD4+ and CD8+ T cells." (PMID 41488655, 2025). "In addition, we found that ovarian tumor tissue culture supernatant had a more significant chemotactic effect on CD4+CCR8+ Tregs, suggesting that some components of the culture supernatant were involved in recruitment." (PMID 37950246, 2023). "In this study, significantly different gene expression profiles were found between peripheral circulating CD4+ T cells and infiltrating CD4+ T cells in ovarian tumor tissues, in which chemokine-chemokine receptor signaling pathway was significantly enriched in all three groups of differential genes." (PMID 37950246, 2023). "In brief, treatment of monocyte-derived DCs with a p38 inhibitor in combination with IL-15 diminished PD-L1 expression and indoleamine 2,3-dioxygenase function, and favored stimulation of ovarian tumor antigen-specific Th1/Th17 CD4+ T cell responses, while also reducing CD4+Foxp3+ Treg expansion." (PMID 33057068, 2020). "It has been recently reported that function of neoepitope-specific CD8+ T-cell from ovarian tumors is significantly higher than PBMCs, suggesting neoepitope-specific CD4+ and/or CD8+ T-cells in TILs could be a useful source of TCR for ACT." (PMID 31221207, 2019). "Although there appeared to be fewer CD4+ T cells in ovarian tumors compared to normal ovaries, there was also a significant variation in CD4+ cell content among hens, which is likely due to variations in follicle content and tumor stage as seen in cell counts obtained using morphometry." (PMID 24040191, 2013). "A TNFR2 antagonists could specifically inhibit CD4+Foxp3+ Tregs expansion in the tumor microenvironment, whereas it had little inhibitory effects on CD4+ Tregs in periphery or from healthy donors, and killed human ovarian tumor cells directly." (PMID 29623079, 2018). "Immunohistochemistry showed a locally higher infiltration of CD4-positive and CD8-positive cells in the uterine tumor compared to the ovarian tumor and scarce presence of CD20-positive cells in both tumors." (PMID 39758791, 2025). "We discovered that SNX10 expression was positively linked with the infiltration of macrophages, neutrophils, dendritic cells, CD4+T cells, and CD8+T cells in ovarian tumor tissue." (PMID 40426851, 2025). "The ligands CCL1 and CCL18 corresponding to CCR8 were significantly overexpressed in ovarian tumor tissues, and the CCR8-CCL1 and CCR8-CCL18 axis played a key role in the migration and infiltration of CD4+CCR8+ Tregs into ovarian tumor tissues." (PMID 37950246, 2023). "In vivo studies demonstrated the prolonged overall survival upon combined treatment of 968 with anti-PD-L1 accompanied by increased granzyme B secretion by CD4+ and CD8+ T cells isolated from ovarian tumor xenografts." (PMID 34944392, 2021). "In our study, we stimulated isolated CD4+ and CD8+ T-cells from tumors with peptide-pulsed CD4−CD8− cells derived from PBMCs, because APCs in ovarian tumor microenvironment have been shown to be dysfunctional or immunosuppressive." (PMID 31221207, 2019). "The analysis of CD11c+, BDCA2+, and CD68+ cells suggests that myeloid DC, plasmacytoid DC and macrophages together constitute less than a total of 5% of each of the CD4+ and CD8+ cells in ovarian tumors." (PMID 24244610, 2013). "Lymphocytes including effector memory CD4+ T cells, NY-ESO-1 tumor specific CD8+ T cells, CD4+ and CD8+ regulatory T cells, and TH17 cells have been found within ovarian tumor microenvironments." (PMID 21935406, 2011). "There were less CD4+ cells than CD8+ and Bu1a+ cells in normal ovaries or ovarian tumors." (PMID 24040191, 2013).
ovarian tumor (continued). "The lower presence of both CD4-positive and CD8-positive T cells in the growing left ovarian tumor than in the uterine tumor suggests that immune tolerance after LP therapy may have occurred, potentially leading to resistance to LP therapy in the left ovarian tumor." (PMID 39758791, 2025). "Likewise, co-incubation of ovarian tumor-derived exosomes but not those derived from normal cells resulted in the expansion of human Tregs which mediated conversion of helper CD4+CD25neg T cells into immunosuppressive CD4+CD25highFOXP3+ Tregs." (PMID 34831378, 2021). "This is consistent with a recent study of human ovarian tumors using similar markers (CD3, CD4, CD8, and CD20) which showed that tumor infiltrating lymphocytes were more prevalent in high-grade serous carcinomas followed by endometrioid ovarian tumors and then other ovarian tumor types." (PMID 24040191, 2013).